RNU6-686P (RNA, U6 small nuclear 686, pseudogene)
Gene: Small nuclear RNA gene on chromosome 15 (65,229,861 to 65,229,967, forward strand). Ensembl gene ENSG00000201709.
Homologues: Orthologues: chimpanzee U6 (99% identical), pig U6 (93% identical), rabbit U6 (90% identical), macaque U6 (89% identical), rat LOC120093901 (85% identical), dog U6 (82% identical), rabbit U6 (82% identical). Paralogues in human: RNU6-140P (90% identical), RNU6-15P (90% identical), RNU6-199P (90% identical), RNU6-211P (90% identical), RNU6-21P (90% identical), RNU6-235P (89% identical), RNU6-25P (89% identical), RNU6-41P (89% identical), RNU6-463P (89% identical), RNU6-480P (89% identical), RNU6-961P (89% identical), RNU6-1 (88% identical), and 1291 more.